STAT4 (signal transducer and activator of transcription 4)
Diseases named in the same sentence as STAT4 in open-access papers (continued):
Sharing a sentence is not in itself a finding about the gene and the disease.
tumor (continued). "STAT1 and STAT4 are genes located on the 2q32 band, which encode for important components of the JAK-STAT signaling pathway, which is (among other processes) involved in apoptosis and oncogenesis, having both tumor suppressive and tumor promoting functions." (PMID 36982172, 2023). "STAT4 is a key mediator of inflammation and tumor development." (PMID 37949959, 2023). "Additionally, STAT4 expression was characterized to be significantly negatively correlated with tumor purity of the majority of cancer types." (PMID 36968603, 2023). "Hence, we proposed that higher STAT1, STAT2, and STAT4 expression suggested less tumor stemness characteristics." (PMID 36968603, 2023). "Analyses of single‐cell datasets implies STAT4 is T‐cell specific in tumor environment." (PMID 38107057, 2023). "It has been theorized that reduced STAT4 expression, induced by the SNP, could potentially weaken the anti-tumor response by affecting STAT4 modulation of interleukin 12 in NK cells." (PMID 37760499, 2023). "Moreover, STAT4 promoted anti‐tumor immune responses comprised Th1, Th17, and IFN‐γ production in HNSCC." (PMID 38107057, 2023). "Furthermore, OCLN promoted the transcription of IL8 through STAT4, ultimately contributing to tumour vascular remodelling and BLCA progression." (PMID 35224833, 2022). "As a member of the STAT family, STAT4 can regulate the expression of inflammatory mediators of T cells and NK cells and plays an important role in a variety of pathophysiological processes such as immunity and tumor growth." (PMID 35136014, 2022). "Furthermore, OCLN overexpression enhanced the activity of the IL8/STAT3 signalling pathway by activating STAT4, ultimately contributing to tumour vascular remodelling and metastasis." (PMID 35224833, 2022). "Contrarily, STAT4 plays a role in tumor progression in colorectal cancer (CRC)." (PMID 34638338, 2021). "STAT4 was reported to be expressed at lower levels in HCC than in normal liver tissues and to be associated with serum hepatitis B surface antigen (HBsAg) level, tumor number, tumor size, and severity of HCC." (PMID 32226303, 2020). "As it can be activated in both tumor cells and immune cells, we suspect that STAT4 may modulate the interaction between tumor cells and host immunity." (PMID 32226303, 2020). "Therefore, the IL12/STAT4 axis is vital for inflammatory cytokines secretion that participates in many diseases and anti-tumor responses." (PMID 32226303, 2020). "STAT4 is a pivotal mediator in inflammation and tumor development." (PMID 32226303, 2020). "Based on the results of the present studies, STAT3 may play a relatively important role in tumor and inflammatory biology, while STAT4 appears to be less involved." (PMID 33505963, 2020). "Interestingly, we also observed a distinct population of CD11b+Ly6CloLy6G− with increased accumulation in the spleens of tumor bearing Stat4−/− mice compared to WT." (PMID 32010142, 2019). "Given the increased expression of immunosuppressive biomarkers observed in T cell and myeloid cell populations of HNSCC tumor-bearing Stat4−/− mice, we determined the cytotoxic potential of lymphocyte populations involved in anti-tumor immune responses against HNSCC." (PMID 32010142, 2019). "All of these molecular changes observed in sentinel lymph nodes of Stat4−/− tumor bearing mice support the crucial role STAT4 plays in the generation of a lymph node anti-tumor microenvironment unconducive to lymphatic metastasis and subsequent dissemination to distant organs during HNSCC." (PMID 32010142, 2019). "The downregulation of Stat1, Stat4 and Stat6 observed in tumour tissue may confirm the reduced response to cytokines of lymphocytes and therefore may indicate a decrease in lymphocyte activation." (PMID 31595196, 2019). "Splenic CD4+ T cells of tumor bearing Stat4−/− mice produced less IL-17 compared to WT mice." (PMID 32010142, 2019).
tumor (continued). "Interestingly, Arg expression in the primary tumor site and spleens were comparable between tumor bearing WT and Stat4−/−mice." (PMID 32010142, 2019). "Similarly, PD-1, a negative regulator of adaptive anti-tumor immunity, was increased in lymph node and splenic CD8+ T cells and splenic CD4+ of metastatic Stat4−/− mice compared to tumor bearing WT mice." (PMID 32010142, 2019). "Hif1a, a transcription factor activated under hypoxic conditions that is conducive to angiogenesis, tumor growth, and metastasis, was also found to be overexpressed in the sentinel lymph nodes, further reflective of an impaired ability in Stat4−/− mice to counteract pro-tumor changes at these sites." (PMID 32010142, 2019). "Increased expression of these immune checkpoint receptors in CD4+ and CD8+ T cells of HNSCC tumor bearing Stat4−/− mice demonstrate the requirement for STAT4 in the inhibition of immunosuppressive T cell pathways and initiation of an appropriate immune response against metastatic HNSCC." (PMID 32010142, 2019). "Interestingly, we observed that CD11b+Ly6Clo Ly6G− cells were more abundant in the spleen and bone marrow of tumor bearing Stat4−/− mice compared to WT." (PMID 32010142, 2019). "Primary tumor volumes were similar between tumor bearing Stat4−/− and WT mice." (PMID 32010142, 2019). "Taken together, our data suggests that although STAT4 deficiency does not affect primary tumor development, STAT4 associated pathways are important in preventing tumor metastasis in experimental HNSCC." (PMID 32010142, 2019). "Interestingly, we observed increased activation of anti-tumor immune-related pathways (STAT4/JAK2 and Type-I IFN signaling) and inhibition of BCSC regulators (β-CATENIN and NF-κB pathways) in HGFL-RON signaling-deficient BCSCs compared to controls." (PMID 28938607, 2017). "STAT4 is canonically activated by cytokines IL‐12 and IL‐23, and while early studies suggested that STAT4 phosphorylation undermines Treg suppressive function by inducing a Th1‐like phenotype that promotes anti‐tumor immunity, emerging data reveal a more nuanced regulatory role." (PMID 40673866, 2025). "In addition, STAT4 regulates tumor cell migration and proliferation." (PMID 39597056, 2024). "The analysis of the STAT4 rs7574865 variant showed that the G allele is associated with a better prognosis of LSCC, namely an early stage of the disease, small tumor size without spread to the surrounding structures, and well-differentiated tumor cells in LSCC." (PMID 39337665, 2024). "Interestingly, in xenograft nude mice model, overexpressed STAT4 decreased tumor growth." (PMID 38107057, 2023). "Notably, STAT4 had the strongest correlations across the majority of TCGA tumor types." (PMID 36968603, 2023). "Interestingly, JAK2 may play a role in keeping the Th-1 cytotoxic answer against the tumor present by mediating the IL-12 signaling and thereby phosphorylating STAT4." (PMID 34948183, 2021). "In addition, STAT4 regulates the migration and proliferation of tumor cells." (PMID 32226303, 2020). "STAT4 might induce inflammation and promote tumor growth by regulating the immune response." (PMID 32984010, 2020). "While STAT4 exerts functions in many tumor cells or immune cells such as T cell and NK cell, we lack insight into whether and how it regulates other kinds of cells, including Tfh cell 27-28, Treg cell 29-30, fibroblast 102, mast cell 145 and endothelial precursor cell." (PMID 32226303, 2020). "Combined with the diminished IFN-γ production observed in tumor bearing Stat4−/− mice, our data supports the hypothesis that STAT4-mediated induction of systemic TH1 and TH17 anti-tumor immune responses is essential for the inhibition of metastasis during HNSCC." (PMID 32010142, 2019).
tumor (continued). "In summary, our results demonstrate that STAT4 is a key mediator in the inhibition of HNSCC tumor metastasis through mechanisms associated with increased T cell immunosuppression MDSC activity and pro-tumor inflammation, as well as a decrease in cytotoxic anti-tumor lymphocytic activity." (PMID 32010142, 2019). "Moreover, TRAMP-C2 cells inhibited the phosphorylation of the transcription factor STAT4, showing that tumor cells concurrently provide positive signals for activation (IL-12R up-regulation) and inhibit intracellular signals downstream of the IL-12R (i.e., STAT4)." (PMID 24212972, 2011). "Conversely, TCN1 overexpression upregulated DUOX2 expression and promoted EMT, and this effect was abolished by STAT4 knockdown, indicating that TCN1 regulates DUOX2 through STAT4 to drive EMT-mediated tumor aggressiveness." (PMID 41154358, 2025). "JASPAR prediction and ChIP-qPCR confirmed the recruitment of STAT4 to the enhancer region, leading to transcriptional upregulation of CXCL11 and subsequent NK cell infiltration, which exerted an anti-tumor effect." (PMID 40576244, 2025). "Activation of STAT1, STAT2, STAT3, STAT4, and STAT6 was observed in expanded bile duct epithelium and tumor cells, while expression of STAT5a and STAT5b was found in macrophages and connective tissues surrounding the tumor." (PMID 39290697, 2024). "In an orthotopic liver tumor model, AAV-mediated expression of IL-12 induced IL-12R signaling (STAT4 phosphorylation), and led to IFN-γ production, infiltration of T cells and to tumor regression in a vector dose-dependent manner." (PMID 38558809, 2024). "We found that STAT4 is most closely related to the prognosis and tumor immunity of AML, so we explored the function and mechanism of STAT4 in AML." (PMID 38294290, 2024). "Taken together, it was implied that up-regulation of STAT2, STAT4, and STAT5B meant down-regulation of HNSC tumor stemness characteristics." (PMID 36968603, 2023). "TFs in XIST+ and S100A4+ tumor cells were similar, particularly RUNX3, REL, STAT4, and E2F1, which regulate the EMT process." (PMID 37430270, 2023). "PPI network analysis revealed these genes and modules were mainly related to tumor progression (LOXL1, IKBKE, LNX1, FOXA2, FGF17, and FGF2) and immune response (STAT4, IL23R, LTA, ITK, and IL19)." (PMID 36611170, 2023). "On the whole, it was illustrated that higher the expression of STAT1, STAT2, STAT3, STAT4, STAT5A, and STAT5B, the lower the tumor purity." (PMID 36968603, 2023). "Collectively, the composition of CDH4, STAT4, and LMP1 constitutes an ideal model for disease diagnosis as well as for monitoring tumor malignancy." (PMID 37393410, 2023). "Taken together, we concluded that a tumor sample with high STAT1, STAT2, STAT4, and STAT5B expression levels tended to be enriched in T cell dysfunction phenotypes, while STAT6 showed to be the opposite." (PMID 36968603, 2023). "Apart from the PI3K/AKT pathway (CDC37, IL6R), Epidermal-Mesenchymal transition (IL6R, SHC2), tumour metastasis and T1/T2 activation are highlighted (DLL1, STAT4, IL6R)." (PMID 36834486, 2023). "Demonstrating the prognostic role of STAT4 in our collected cohort of 86 TNBC samples, STAT4 protein was highly expressed in tumor tissues compared to that in paired normal tissues, which was consistent with previous report." (PMID 38107057, 2023). "Analysis of DEGs revealed an upregulation of STAT1, STAT4, and CXCL11, indicating the activation of anti-tumor and immunomodulatory pathways." (PMID 37842640, 2023). "In general, it was displayed that higher expression of STAT1, STAT2, STAT3, STAT4, and STAT5A indicated a lower tumor purity." (PMID 36968603, 2023). "Signal transducer and activator of transcription 4 (STAT4) is a critical transcription factor for T helper cell differentiation and tumor cells." (PMID 38107057, 2023). "IHC analyses showed stronger CDH4, STAT4, and CYLD immunoreactivity in adjacent basal epithelium compared with that in tumor cells (p < 0.001)." (PMID 37393410, 2023).
tumor (continued). "IL-7–CBD provided prosurvival signals mediated by STAT5 activity to tumor-resident T cells, while CBD–IL-12 provided immune-activating signals mediated by STAT4 activation." (PMID 38019919, 2023). "The signal transducer and activator of transcription 4 (STAT4), a member of the STAT family, increases Th1 cell differentiation and IFNγ production in immune cells and regulates tumor cell migration and proliferation." (PMID 35873566, 2022). "This may be attributed to the increased tumor burden in advanced stages, or to the pathogenetic role of these molecules in disease progression, as, in two studies using cell lines, the activity of STAT5/BIC/miR-155 and JAK/STAT3/STAT4/miR-146a pathways was associated with disease progression." (PMID 36613718, 2022). "With increasing levels of tumor PD-L1, the expression of transcription factors for Th1, Th2, or M1 macrophages, including NFKB1, GATA3, HIF1A, STAT4, TBX21, IRF8, and STAT1, was downregulated." (PMID 33754038, 2021). "Studies have shown that STAT4 is involved in the occurrence and development of HCC and other tumors, and the abnormal expression of STAT4 is closely related to tumor metastasis and prognosis." (PMID 34100914, 2021). "Compared to normal samples, the expression of E2F2, FOXJ1, EMX1, PAX7, NKX6-1, FOXD1, and ZNF552 was significantly higher (P < 0.05) and the expression of MSX1, STAT4, NR3C2, and EGR3 was significantly lower in tumor samples (all P < 0.05)." (PMID 33688372, 2021). "IL-12 is a strong proinflammatory cytokine that induces a signaling pathway in which STAT4 and IFNG are key for anti-tumor responses." (PMID 32973967, 2020). "Early stages of tumor growth were marked by robust T cell activation, including expression of cytotoxic mediators such as PRF1, GZMB, and IFN-γ, and dynamic polarization supported by IL-12 and STAT4." (PMID 41278869, 2025). "Collectively, the data point to a functional connection among TCN1, STAT4, and the DUOX2/ROS axis that, by modulating oxidative stress, may constitute a tumor cell–autonomous oncogenic route in PDAC." (PMID 41154358, 2025). "Immunofluorescence staining also showed that the JAK‐STAT1 pathway was activated (high STAT4+) in tumour‐infiltrating T cells, whereas the PDCD1+ ratio was not significantly different." (PMID 39658531, 2024). "Binary logistic regression analysis of STAT4 rs7574865, rs7601754, and rs10168266 did not reveal statistically significant results in the T4 subgroup of tumor size." (PMID 39337665, 2024). "This interaction suggests a coordinated regulatory mechanism in which p-STAT4 and CBP may synergistically influence expression of c-MYC and ultimately lead to tumour progression and docetaxel resistance." (PMID 38429845, 2024). "STAT4 plays a critical role in IL12 response and functions in the development of the Th1 and Th2 lymphocytes, and interferon gamma signaling in response to the stimulation of cytokines, which is important in the modulation of tumor immunity." (PMID 37393410, 2023). "The average expression values of STAT1 (p < 0.001), STAT2 (p < 0.001), STAT3 (p < 0.001), STAT4 (p < 0.001), STAT5A (p < 0.001), STAT5B (p < 0.001), and STAT6 (p < 0.001) among immune subtypes C1-C6 in all tumor types were identified to have notable differences." (PMID 36968603, 2023). "Likewise, the differences in the expression levels of STAT2, STAT3, STAT4, STAT5A, STAT5B, and STAT6 between normal and tumor tissues were also displayed." (PMID 36968603, 2023). "To further evaluate the prediction power of candidate biomarkers that have greater likelihoods of becoming clinically useful markers for NPC diagnosis and for monitoring tumor progression, we built multiple logistic regression models considering the expression of CDH4, STAT4, CYLD and LMP1." (PMID 37393410, 2023). "Consequently, we deduced that high expression of STAT1, STAT2, STAT4, and STAT5A indicated low BRCA tumor purity." (PMID 36968603, 2023).
tumor (continued). "Thus, higher the expression of STAT1, STAT2, STAT3, STAT4, STAT5A, and STAT5B, the lower the tumor purity." (PMID 36968603, 2023). "Several previous studies found that the mRNA expression of STAT4 in HCC tumor tissues was significantly lower than that in adjacent nontumor liver tissues." (PMID 35136014, 2022). "However, STAT3 and STAT5 have been studied more thoroughly, while the role of STAT1, STAT2, STAT4, and STAT6 in tumor development has been studied less thoroughly." (PMID 35244291, 2022). "STAT2, STAT4 and STAT6 appear to have more limited roles in tumor biology." (PMID 35163491, 2022). "STAT4 is an important transcriptional activator of JAK/STAT signaling pathway, and plays an important role in the body’s immune response, antiviral infection, and promotion of tumor cell invasion and metastasis." (PMID 34100914, 2021). "Furthermore, STAT5 overexpression downregulates STAT4 and SATB1 expression through the induction of microRNA-155 (miR-155), empowering tumor immune response escape mechanisms and decreasing the secretion of anti-tumor molecules, such as IFNγ." (PMID 34685762, 2021). "Specific SNPs in STAT4 and IFNG could be key for the promotion of the IL-12 pathway anti-tumor actions in NK, macrophages and T cells." (PMID 32973967, 2020). "High expression of STAT4 has been shown to be a positive prognostic factor in liver cancer, breast cancer, and ovarian cancer, whereas its overexpression in CRC is positively correlated with the depth of tumor invasion." (PMID 33505963, 2020). "Similar trends were found in Ifng gene expression in tumors, lymph nodes and spleens of tumor bearing Stat4−/− mice, although not statistically significant." (PMID 32010142, 2019). "Taken together, the reduction in cytotoxic lymphocyte activity observed systemically, as well as in metastatic but not primary tumor sites of Stat4−/− mice, potentially contributes to metastasis in experimental HNSCC." (PMID 32010142, 2019). "First, we observed significant reduction in CD4+ T cells in lymph nodes of all tumor bearing WT and Stat4−/− mice compared to non-tumor bearing mice." (PMID 32010142, 2019). "It is noteworthy that expression levels of VegfA and Hif1a are higher in metastatic lymph nodes of WT and Stat4−/− mice compared to primary tumors and non-metastatic lymph nodes of tumor bearing mice." (PMID 32010142, 2019). "Interestingly, subjects with GG genotype at rs7574865 had the lowest mRNA levels of STAT4 in both HCC and non-tumor tissues compared with TG and TT genotypes." (PMID 23990947, 2013). "Furthermore, STAT4 and STAT5 are essential for the development of efficient NK-cell anti-tumor surveillance and inhibiting this may have also contributed to lack of efficacy." (PMID 38297352, 2024). "Consequently, KRAS*‐STAT4‐mediated upregulation of the Y chromosome KDM5D contributes significantly to sex differences in KRAS*CRC by disrupting cancer‐cell adhesion properties and tumor immunity." (PMID 38222317, 2024). "Here, STAT4 overexpression inhibited tumor growth without STAT3 dependent in nude mice model." (PMID 38107057, 2023). "Consequently, we could conclude that the higher expression of STAT3, STAT4, STAT5A, STAT5B, and STAT6, the higher differentiation degree and less tumor stemness characteristics of BRCA tumor cells." (PMID 36968603, 2023). "We focused on the role of STAT4 as a transcription factor in tumour angiogenesis and sought to explore whether OCLN mediated the transcription of IL8 via STAT4 as an approach to further verify the role of STAT4 in OCLN‐mediated regulation of IL8 expression in BLCA angiogenesis." (PMID 35224833, 2022). "Moreover, overexpression of activated STAT4 was shown in epithelial cells of ovarian cancer, which correlated with poor clinical outcome and progress to metastasis by a different mechanism, including EMT and interaction with tumor stroma." (PMID 34638338, 2021).